CRP (C-reactive protein)
Diseases named in the same sentence as CRP in open-access papers (continued):
Sharing a sentence is not in itself a finding about the gene and the disease.
urticaria (continued). "In children with single episode of urticaria UAS correlated with CRP level." (PMID 24490166, 2013). "It was shown that D-dimer was closely related to the activation of urticaria as well as CRP levels." (PMID 24490166, 2013). "In children with urticaria serum level of CRP was significantly higher than in the control group." (PMID 24490166, 2013). "In children with single episode of urticaria UAS correlated with CRP levels (r = 0.43; P < 0.005)." (PMID 24490166, 2013). "In addition, the urticaria-like rash on her body persisted and her CRP level remained elevated." (PMID 26590045, 2015). "This patient fulfilled Strasbourg criteria: 2 major criteria, recurrent urticaria and gammopathy, and 3 minor criteria, fever, raised ESR and CRP levels, and neutrophilic urticarial histopathology." (PMID 39493365, 2024). "We measured IgE and CRP serum levels in 47 CSU patients (and 45 healthy controls) and determined CSU disease activity using the urticaria activity score (UAS7)." (PMID 37632245, 2023). "The markers we used were CRP, troponin, LDH, which are involved in urticaria exacerbation, as shown by other studies." (PMID 34574918, 2021). "In order to find a relationship between laboratory parameters and urticaria severity, the variables ASST, D-dimer, and CRP were related to the UAS of the day before the exams." (PMID 33640190, 2021). "CRP was significantly higher in the AU group than in the CSU group, and patients with urticaria had significantly higher levels of CRP than those in the healthy controls (P < 0.05)." (PMID 27057079, 2016). "Children with recurrent urticaria and infection revealed a positive correlation of IL-1RA level with WBC and CRP concentration (r = 0.9; P < 0.03, for both)." (PMID 24490166, 2013). "In patients with severe refractory urticaria accompanied by arthralgias with/or without fever and elevated CRP, further laboratory testing must be performed to identify Schnitzler syndrome as a potential diagnosis." (PMID 37496089, 2023). "Besides CRP, serum ESR should be considered in patients with severe urticaria refractory to treatment." (PMID 33235810, 2020). "Serum concentrations of C-reactive protein (CRP) and interleukin 6 (IL-6), key markers of acute phase response and of D-dimer, a marker of fibrin turnover were investigated in 58 CSU patients assessed with the urticaria activity score (UAS) and the controls." (PMID 30026764, 2018). "Moreover, IL-1RA level was correlated with IL-1β level, CRP, and D-dimer levels in children with single episode of urticaria and WBC and D-dimer concentration in children with the recurrence of urticaria." (PMID 24490166, 2013). "We documented that IL-1β and IL-1RA level in infected and noninfected children with urticaria correlate differently with D-dimer and the markers of inflammation including CRP and WBC." (PMID 24490166, 2013). "Basic laboratory workup for CSU, including differential blood count (DBC), C-reactive protein (CRP), total serum IgE, and IgG anti-TPO, recommended by the latest international EAACI/GA2LEN/EuroGuiDerm/APAAACI urticaria guideline, may thus help identify type IIb CSU." (PMID 39483682, 2024). "Current international urticaria guidelines recommend the following basic tests for all patients with CSU: differential blood count and CRP (to help rule out an underlying systemic disease) and total IgE and anti-thyroid peroxidase levels (which are important for predicting treatment response)." (PMID 39654029, 2024). "WBC and CRP only indicated the inflammatory response existing in patients with urticaria; they could not distinguish between patients with severe or mild disease." (PMID 27057079, 2016). "Regarding inflammatory biomarkers, such as ESR and CRP, we found a decrease of both, even if just ESR was significant, suggesting that omalizumab decreases urticaria signs and symptoms not just subjectively (as tested by UAS7), but also objectively." (PMID 33235810, 2020).
Airway obstruction (29 papers, 2006 to 2025). Obstruction of conducting airways of the lung. "Elevated CRP levels, on the other hand, have been associated with the severity of airway obstruction, an elevated risk of having exacerbations, a poor short-term outcome in patients admitted for these acute episodes, and higher mortality." (PMID 39126034, 2024). "A population-based study revealed that elevated levels of inflammatory biomarkers (IL-6 and CRP) contributed to the association of depressive symptoms with pulmonary obstruction." (PMID 35371847, 2022). "All other measures of COPD morbidity, in particular those of airway obstruction, lung hyperinflation, gas exchange capacity, oxygen saturation, physical capacity, exacerbation risk and CRP levels, were only indirectly linked to PNP." (PMID 31959163, 2020). "They reported that severe airway obstruction, in the setting of elevated CRP, increased risk of cardiac injury almost two-fold." (PMID 25480156, 2014). "Our study extends these findings by indicating that a combination of high IL-6 and high CRP as well as a combination of high inflammation and depressive symptoms were associated with mounting levels of pulmonary obstruction." (PMID 23676005, 2013). "In hierarchical models, the significant association of depressive symptoms with pulmonary obstruction was reduced by the presence of IL-6 and CRP." (PMID 23676005, 2013). "Higher CRP concentration has been associated with airway obstruction severity, increased resting energy expenditure, and impaired exercise capacity and quality of life in COPD patients." (PMID 20534161, 2010). "The aim of the present study was to determine the diagnostic accuracy of clinical signs and symptoms and CRP for diagnosing airway obstruction in primary care." (PMID 16670014, 2006). "Additionally, elevated CRP can contribute to the formation of plastic mucus, further increasing the risk of airway obstruction and ACD." (PMID 41234411, 2025). "In our study, CRP tended to be associated with greater airway obstruction." (PMID 27488495, 2016). "This indicates that smoking in a vulnerable population (those with high CRP) might confer an accelerated risk of obstructive lung disease, compared to the elevated inflammatory marker alone." (PMID 20625390, 2010). "Thirdly, serum levels of IL-6 and CRP were also found to be associated with FEV1 and FEV1/FVC measures of pulmonary obstruction." (PMID 23676005, 2013). "This is in agreement with the results obtained in two recent population-based studies, as well as clinical observations of increased IL-6 and CRP levels in clinically stable patients with airway obstruction compared to healthy smoker controls." (PMID 23676005, 2013). "Our study indicates that higher levels of IL-6 and CRP combine to produce greater pulmonary obstruction and depressive symptoms." (PMID 23676005, 2013). "The comparison between the two disorders, showed that CVD, particularly with volume overload, was more frequent in COPD patients, who had also older age, higher BMI, heavy smoking history, increased CRP and greater airway obstruction." (PMID 24004921, 2013). "The relation between CRP and the severity of airway obstruction in COPD was illustrated before in a population based survey, which found an association between FEV1 and CRP." (PMID 16670014, 2006). "As compared with patients with COPD alone, patients with COPD combined with OSA were overweight, had poorer sleep quality, less acute exacerbation (AE) of COPD in the prior year, more underlying diseases, but lower C-reactive protein (CRP) and better airway obstruction (all p < 0.05)." (PMID 37008211, 2023). "Similar results were also reported by Gupte and colleagues who found that prior TB infection associated with an excess loss of FEV1, and that although older age, smoking and higher CRP associated with obstructive lung disease, CD4 count and ART did not." (PMID 31830103, 2019).
Airway obstruction (continued). "Our mediational analyses indicated a strong association of depressive symptoms with spirometric measures of pulmonary obstruction independent of conventional risk factors, but the significance of this association was reduced by the addition of IL-6 and CRP into the hierarchical model." (PMID 23676005, 2013). "Patients with COPD also have an elevated CRP level, and CRP can independently predict the prognosis of COPD in participants with airway obstruction." (PMID 35987624, 2022). "We indeed found that a small proportion (2%) of the effect of BMI on FVC was mediated by CRP, and 8.8% of the BMI effect on FEV1 was explained by inflammatory mechanisms suggesting indirect effects of BMI on airway obstruction through systemic inflammation." (PMID 34154662, 2021). "Signs of systemic inflammation are present in the circulation of COPD patients with mild to severe airflow obstruction, including elevated leukocyte counts and levels of C-reactive protein (CRP) relative to individuals with no airway obstruction." (PMID 39256247, 2025). "In conclusion, the present study confirms that circulating CRP levels are higher in stable COPD patients than in healthy individuals and are a significant long-term predictor of future COPD outcomes in individuals with airway obstruction." (PMID 24396422, 2014). "One useful predictor for OAD could be C-reactive protein (CRP), as it is related with irreversible airway obstruction due to some kind of systemic inflammation." (PMID 16670014, 2006). "It is surprising, however, that AATD COPD patients had lower blood levels of CRP (compared to non-AATD COPD patients) but yet exhibited similar, if not greater, airway obstruction." (PMID 24975928, 2014).
Aortic dissection (29 papers, 2013 to 2025). Aortic dissection refers to a tear in the intimal layer of the aorta causing a separation between the intima and the medial layers of the aorta. "For instance, the high risk of acute aortic dissection (AAD) in patients was predicted to be associated with elevated levels of c-reactive protein (CRP) (9.71 mg/L), high serum phosphorus (P) levels (0.37 mmol/L), elevated procalcitonin (PCT) levels (0.447 ng/mL), and the use of enteral nutrition." (PMID 38789951, 2024). "A role for CRP may instead be considered for follow-up, as the stratification of patients with aortic dissection and studies have described an association between this acute-phase protein and the period of hospitalization." (PMID 35892496, 2022). "The elevated white blood cell and C-reactive protein reflect the inflammation due to aortic dissection." (PMID 40718171, 2025). "Recently, Erdolu and as suggested the use of CRP and neutrophil to lymphocyte ratio values to predict mortality in patients with aortic dissections." (PMID 35892496, 2022). "Mounting evidence indicates that changes in inflammatory biomarkers, such as white blood cell (WBC) count, C-reactive protein (CRP), and D-dimer, are associated with acute-phase reactions as well as adverse events in acute aortic dissection patients." (PMID 35071351, 2021). "The time to the peak level of hs-CRP was shorter and the duration of persistently high hs-CRP level was longer in the aortic dissection with complication patients." (PMID 32034642, 2020). "In the recent study, a combination of tenascin-C and D-dimer or CRP can improve the performance of predicting in-hospital death from acute aortic dissection." (PMID 32034642, 2020). "Clinical and laboratory data indicated that patients with TAD were predominantly older men, exhibiting elevated leukocyte, neutrophil, and monocyte counts, alongside markedly increased C‐reactive protein (CRP) levels, reflecting an acute inflammatory response at the onset of aortic dissection onset." (PMID 40171827, 2025). "A growing body of literature has shown that inflammatory cells, such as WBCs, CRP, neutrophils, platelets, and a combination of neutrophils/platelets and lymphocytes, play an important role in the development and progression of aortic dissection." (PMID 36740681, 2023). "Furthermore, acute-phase reactants, like CRP or SAA, were associated with aortic injury, including aortic aneurysm and aortic dissection, in atherosclerotic disease." (PMID 35996028, 2023). "Elevated plasma d-dimers and hypersensitive CRP have been studied in patients with aortic dissection, but their roles in screening for thoracic aneurysm are yet unknown." (PMID 36148051, 2022). "And it is a retrospective rather than a prospective study, so large-scale, multi-center clinical studies are required to further confirm the application value of blood biomarkers including D-dimer, FIB, PLT, CRP, WBC, and NEU in surgical risk assessment of patients with aortic dissection." (PMID 34548604, 2021). "Several laboratory indexes on admission such as D-dimer, C reactive protein (CRP), fibrinogen, platelet count, and white blood cell count (WBC) have been proven to be associated with early mortality in patients with aortic dissection." (PMID 31941543, 2020). "Indeed, high-sensitivity C-reactive protein (hs-CRP) is used to predict in-hospital events in patients with acute aortic dissection." (PMID 32034642, 2020). "Thus, further studies with more patients from multicenter are needed to determine the exact significance of CRP in acute aortic dissection." (PMID 29254149, 2017). "And there was a significant positive correlation between VTI and CRP (r = 0.670, P < 0.001), Previous studies have reported that elevated plasma CRP levels were found in patients to predicting in-hospital clinical events of aortic dissection." (PMID 26555752, 2015).
Aortic dissection (continued). "In addition, CRP levels positively correlate with DD levels in aortic dissection, suggesting the presence of a strict relationship between these two factors in the pathophysiology of the complication and with plasma MMP8 and MMP9 in patients suspected of dissection." (PMID 35892496, 2022). "Predictive efficacy of the NLR, CRP, PCT, and sputum smear forVAP after Stanford type A aortic dissection surgery." (PMID 40026526, 2025). "A combined detection model using preoperative blood CRP, D-dimer, and serum MMP-9 concentrations showed AUC value of 0.88 with 70.70% sensitivity and 96.84% specificity for mortality of patients with Type A aortic dissection within 1 year." (PMID 39910669, 2025). "The combined prediction using the NLR, PCT, CRP, andsputum smear is significantly better than using each indicator alone, indicatingthat this approach is highly valuable for the early diagnosis of VAP afterStanford type A aortic dissection surgery." (PMID 40026526, 2025). "A number of studies found that blood or lung tissues from aortic dissection and thoracic aortic aneurysm patients with postoperative ALI showed significant increases in C-reactive protein (CRP), interleukin-6 (IL-6), and monocyte chemoattractant protein-1 (MCP-1)." (PMID 37636294, 2023). "CRP, a circulating and nonspecific inflammatory biomarker, has been shown to be elevated and varied with different stages of aortic dissection." (PMID 25592634, 2015). "Second, aortic dissection is involved in the development of nonbacterial arterial inflammation, which is determined according to a high serum CRP level with a negative procalcitonin test." (PMID 23843799, 2013). "Furthermore, most patients with SCAD were negative for CRP, whereas many patients with aortic dissection presented CRP positivity, providing insights into disease progression." (PMID 40821280, 2025). "In the present case, a high serum C-reactive protein (CRP) level with a negative procalcitonin test and increased serum creatinine kinase BB isozyme (CK-BB) and blood D-dimer levels were helpful in diagnosing slowly progressive and painless aortic dissection." (PMID 23843799, 2013).
arteriosclerosis (29 papers, 2006 to 2025). A vascular disorder characterized by thickening and hardening of the walls of the arteries. "CRP has been shown to be associated with arteriosclerosis and acute cardiovascular events, and has been widely used to stratify patients at high-risk for acute coronary events." (PMID 17178005, 2006). "It is speculated that the determination of serum CRP level could be used to assess the risk of arteriosclerosis and screen for skeletal muscle reduction." (PMID 34957238, 2021). "Persistent high levels of CRP have been well correlated to risk of arteriosclerosis and CVD." (PMID 34640478, 2021). "It is known that C-reactive protein (CRP) is an independent risk factor for arteriosclerosis." (PMID 24967416, 2014). "It is of high possibility to cause thrombosis with the exposure of plasma cholesterol (aggravating arteriosclerosis) and C-reactive protein." (PMID 37000101, 2023). "Compared with age and MAP, factors including baseline resting heart rate, FBG, L-DLC, hs-CRP, and uric acid had less effect on the trajectories of arteriosclerosis." (PMID 37051065, 2023). "CRP also upregulates the release of pro-inflammatory cytokines and inhibits the release of NO, which precedes the development of arteriosclerosis." (PMID 36362055, 2022). "Oral or topical application of RVE1 prevents vascular inflammation and arteriosclerosis and reduces systemic CRP levels." (PMID 33849519, 2021). "CRP also upregulates the release of the pro-inflammatory cytokines and inhibits the release of nitric oxide which precedes the development of arteriosclerosis." (PMID 34679610, 2021). "C-reactive protein (CRP) is one of the most important biomarkers for arteriosclerosis and cardiovascular disease." (PMID 24866016, 2014). "Subsequently, the correlation of fibrinogen and CRP to ND1 mtDNA plasma levels in CABG patients might be triggered by arteriosclerosis, questioning the specificity of ND1 mtDNA plasma levels." (PMID 32629885, 2020). "The positive association of PM2.5 with CRP and SAA, two inflammation markers that have been related to arteriosclerosis and other cardiovascular diseases, is consistent with previous reports of associations between air pollution and traffic exposure with acute-phase inflammation." (PMID 24647077, 2014). "Alternatively, candesartan might be less effective in patients with advanced arteriosclerosis with regard to Hs-CRP, VACM-1 and U-8-OHdG." (PMID 23034088, 2012). "One of the mechanisms is that high LDL levels in atherosclerosis induce endothelial cells to express CRP, which increases the expression of the endothelial receptor for oxidized low-density lipoprotein (LOX-1) and promotes the occurrence of arteriosclerosis." (PMID 34957238, 2021).
coronary artery calcification (29 papers, 2010 to 2026). Calcification of the coronary artery, used as a measure of coronary atherosclerosis, a risk factor for myocardial infarction. "In one study it improved risk prediction beyond that of coronary artery calcification, family history, and high-sensitivity C-reactive protein." (PMID 37629447, 2023). "Therefore an elevated Ca×PO4 product and C-reactive protein have been associated with coronary artery calcification and increased cardiovascular mortality in hemodialysis patients." (PMID 25340109, 2012). "Previous studies have proved that in patients with CRF, the levels of serum CRP, IL-6 and other inflammatory factors are positively correlated with the degree of coronary artery calcification." (PMID 34901204, 2021). "However, adjusted mediation analyses did not detect any indication of a causal mediation pathway linking the effects of sarcopenic status on coronary artery calcification score, C-reactive protein, serum albumin, or 25(OH) vitamin D levels to MACE outcomes." (PMID 39315011, 2024). "Although inflammatory markers, such as CRP, IL-1β, and IL-6, are associated with cardiovascular diseases, OPG is a unique biomarker in that elevated levels have independently correlated with progression of coronary artery calcification." (PMID 20307322, 2010).